DNMT3B (DNA methyltransferase 3 beta)
Diseases named in the same sentence as DNMT3B in open-access papers (continued):
Sharing a sentence is not in itself a finding about the gene and the disease.
tumor (continued). "Our findings demonstrate for the first time that DNMT3A and DNMT3B overexpression may contribute to radiotherapy failure, and their inhibition might be a promising radiosensitizing strategy, mainly in the treatment of patients with metastatic or recurrent RMS tumours." (PMID 34831178, 2021). "In addition, no apparent changes in DNMT3A and DNMT3B were observed in tumor cells." (PMID 32154082, 2020). "Furthermore, APC (p < 0.0001), ASXL1 (p < 0.0001), DNMT3B (p = 0.001), PARP4 (p = 0.002), MET (p = 0.01), TOP1 (p = 0.01), KDR (p = 0.01), SRC (p = 0.01), PAK1 (p = 0.015), ALK (p = 0.02), and MYC (p = 0.03) alterations were found to be more common in tumor samples from AO mCRC patients." (PMID 33194656, 2020). "Immunohistochemistry may be the only method capable of detecting widely scattered nuclear reactivity: analyses of mRNA and protein in tissue and serum samples using other methods may not be able to demonstrate DNMT3B expression in only a small number of scattered tumour cells." (PMID 22394436, 2012). "The results showed that F. nucleatum and its culture supernatant did not increase the activity of DNMT1 and DNMT3B in COLO 205 cells or the activity of DNMT1, DNMT3A, and DNMT3B in subcutaneous tumor tissue of nude mice infected with F. nucleatum." (PMID 40458404, 2025). "Most importantly, the expression of TAT was significantly decreased in tumor cells with a high expression of DNMT3A and DNMT3B, and there was an obvious negative correlation between TAT and DNMT3A/3B." (PMID 39334853, 2024). "In this study, the expression of DNMT1 significantly increased in After Tumor, whereas the expression of DNMT3A and DNMT3B did not change." (PMID 38136558, 2023). "Consistent with cultured cells, was the marked increase of DNMT3B expression—but not DNMT1 and DNMT3A—in GLO1-depleted MDA-MB-231 tumor xenografts when compared with control tumors." (PMID 36998085, 2023). "In a statistical study with TNM staging and history of chronic pancreatitis, DNMT3A and DNMT3B, but not DNMT1 expression, correlated with tumor size." (PMID 24822169, 2014). "The tumor suppressor effect of DNMT3A was demonstrated in a mouse squamous-cell carcinoma model, which became even more aggressive in the concomitant absence of Dnmt3b." (PMID 39819598, 2025).
infection (17 papers, 2012 to 2022). The state of being infected such as from the introduction of a foreign agent such as serum, vaccine, antigenic substance or organism. "Further research into the cell-specific role of Dnmt3b in host defense to infection is, therefore, warranted." (PMID 35269409, 2022). "In our result, we have shown a significant decrease in levels of DNMT1, DNMT3A, and DNMT3B following SARS-CoV-2 in vitro infection." (PMID 33679887, 2021). "Consistently, methylation of miR-145 was significantly greater in tumors, and well correlated with increased expression of DNMT3B, which was influenced by infection with EBV and HPV." (PMID 34946098, 2021). "The highest level of repression (79.0%) of luciferase activity occurred in HUVECs transfected with pGL4.12_ -508/+255 following infection with by Ad-DNMT3B." (PMID 32067910, 2020). "The mRNA level of DNMT3b in HuH-7 cells was decreased by infection of lentivirus expressing sh-DNMT3b (p < 0.05), while that of THBS1 in HuH-7 cells infected with lentivirus expressing oe-THBS1 was increased (p < 0.05)." (PMID 31847842, 2019). "Levels of DNMT1 mRNA fell markedly at 6 h post-infection, while those of DNMT3a and DNMT3b fell only slightly at 12 h post-infection." (PMID 29717211, 2018). "After infection we obtained polyclonal cell populations expressing a specific DNMT3B isoform or DNMT3L in DKO8 and 3BKO cells." (PMID 27121154, 2016). "Additional investigations have pointed to the role of Dnmt3b in the host response during infection." (PMID 35269409, 2022). "Collectively, these results suggest that infection with EBV or HPV modulates the expression of DNMT3B, which may function in the methylation of miR-145 in OSCC." (PMID 34946098, 2021). "Collectively, these results suggest that infection with EBV, alone or jointly with HPV, down-regulates miR-145 expression in OSCC tissue via de novo hypermethylation by induction of DNMT3B." (PMID 34946098, 2021). "To elaborate on the relationship between DNMT3B and HOXB13, we used lentiviral infection to knock down or overexpress DNMT3B in the HCT116 and RKO cell lines, and the efficiency of DNMT3B knockdown and overexpression was assessed by western blotting." (PMID 31815008, 2019). "Recently, it was also shown that following infection of germinal centre (GC) B cells, EBV down-regulates DNMT1 and DNMT3B expression, whilst upregulating DNMT3A." (PMID 23189137, 2012). "Next, expression of these three DNMTs protein was detected by western blotting; the results were consistent with mRNA levels, showing that DNMT1, but not DNMT3a and DNMT3b, protein was down-regulated obviously at 12 h post-infection." (PMID 29717211, 2018). "At every 24 hours within 4 days after lentiviruses infection of SiHa and CaSki, we used Q-PCR to analyze the expression of E6, E7, DNA methyltransferase genes (DNMT1, DNMT3A, DNMT3B and DNMT3L), and tumor suppressor genes (MT1G, NMES1, RRAD, SFRP1, SPARC and TFPI2)." (PMID 26329329, 2015). "Dnmt3b ablation in mouse AEC2 did not impact CXCL1 production, neutrophil influx or bacterial clearance after infection with Pseudomonas." (PMID 33793661, 2021). "To confirm that the DNMT3B-mediated CREG gene hypermethylation is a general mechanism, we further measured the expression of CREG in HCAECs with or without infection with an adenovirus overexpressing DNMT3B expression." (PMID 32067910, 2020). "Quantitative measurement of the mRNAs of DNMT1 DNMT3a and DNMT3b by real-time qRT-PCR reveals that the mRNAs of all the three major form of DNMTs are present in PT cells and PPV infection does not change their levels significantly." (PMID 24392033, 2013). "Importantly, whereas flagellin was not required for the role of Dnmt3b in Pseudomonas induced CXCL1 expression in BEAS-2B cells in vitro, Dnmt3bfl/flCc10Cre mice only demonstrated an enhanced innate immune response after infection with WT PAK but not after infection with flagellin deficient PAKflic." (PMID 33793661, 2021).
hematological malignancies (8 papers, 2016 to 2025). "DNMT3B caused the generation of abnormal methylation during the development of hematologic malignancies." (PMID 36797244, 2023). "Although low-frequency mutations in the DNMT3B gene are found in human hematological malignancies, the role of DNMT3B was well documented in mouse hematopoiesis." (PMID 36614080, 2022). "Given the large magnitude of promoter hypomethylation observed in various mouse hematologic malignancies, it is possible that loss of Dnmt3a and Dnmt3b maintenance activity drives tumorigenesis due to the inappropriate expression of genes normally silenced." (PMID 27563627, 2016). "DNMT1 has been a focal point for mechanistic studies Involving decitabine and bortezomib in hematological malignancies, nevertheless mechanisms regarding DNMT3a and DNMT3b activity remain largely unclear upon treatment with these drugs." (PMID 34358067, 2021). "For instance, mice expressing Dnmt3bCI developed hematologic malignancies with decreased incidence relative to Dnmt3b+/− mice." (PMID 33450231, 2021). "DNMT3B mainly affected the progression of hematologic malignancies." (PMID 36797244, 2023). "However, contradictory studies were published regarding DNMT3b expression in hematological malignancies." (PMID 36614080, 2022). "Finally, we examined the endogenous expression of miR29b and its target DNMT3B in freshly purified plasma cells (CD138+) from bone marrow of 20 MGUS and 25 MM patients relative to control patients with benign hematological diseases." (PMID 38654298, 2024).
genetic diseases (7 papers, 2018 to 2025). "The failure to reacquire normal methylation patterns following rescue of DNMT3B’s catalytic capacity, and the consequential lack of phenotypic rescue, illustrate the challenges in treating genetic diseases that affect the entire epigenome." (PMID 31738163, 2019).
adenocarcinoma (4 papers, 2008 to 2021). A common cancer characterized by the presence of malignant glandular cells. "At the same time, DNMT3B polymorphism may be responsible for susceptibility to colorectal adenomatous polyps and adenocarcinoma." (PMID 33061956, 2020). "Nevertheless, other studies investigating haplotype in other DNMT3B polymorphisms reveal that −579G>T and −283T>C is a haplotype that could affect the DNMT3B’s expression, and the combined genotype −283T/−579G achieved a reduced risk of adenocarcinoma, in comparison with −283C/−579T." (PMID 27876061, 2016).
bacterial infection (3 papers, 2021 to 2022). "More recent studies implicated Dnmt3b in the regulation of the host immune response during bacterial infection in general and P. aeruginosa infection in particular." (PMID 35269409, 2022). "Therefore, further investigations are needed to determine whether complementary mechanisms mediated by Dnmt3a occur in Dnmt3b deficient cells during bacterial infection." (PMID 33793661, 2021). "DNA methyltransferase 3b (Dnmt3b) has been suggested to play a role in the host immune response during bacterial infection." (PMID 35269409, 2022). "Respiratory epithelial cells producing low levels of DNMT3B expressed higher levels of CXCL1 and CXCL8, which was associated with increased neutrophil recruitment during bacterial infections." (PMID 36078063, 2022).
hematological cancers (3 papers, 2020 to 2023). "Overexpression of DNMT1, DNMT3A, and DNMT3B has been observed in many solid and hematological cancers, including MM." (PMID 36059621, 2022).
prostate (3 papers, 2012 to 2022). "RAD9 was epigenetically regulated by DNMT1 and DNMT3B, and subsequent RAD9 overproduction promoted prostate tumorigenesis by targeting hypermethylation." (PMID 34904288, 2022). "RAD9 was epigenetically regulated by DNMT1 and DNMT3B, and subsequent RAD9 overproduction promotes prostate tumorigenesis by targeting hypermethylation." (PMID 34970791, 2022).
autosomal recessive disease (2 papers, 2008 to 2021). Autosomal recessive form of disease. "ICF is a rare autosomal recessive disease characterized by a lack of DNMT3b activity, which causes a DNA methylation depletion, which further leads to reactivation of transposons." (PMID 33750457, 2021).
benign tumors (2 papers, 2012 to 2023). "Of the mucious tumors, the expression of DNMT3a, DNMT3b, and DNMT1 was not different between malignant and benign tumors." (PMID 22768205, 2012).
metabolic disease (2 papers, 2019 to 2022). A congenital disorder (due to inherited enzyme abnormality) or acquired (due to failure of a metabolically important organ) disorder resulting from an abnormal metabolic process. "Whether maternal endometrial DNMT3B knockout has long-term effects on F1 generation, such as whether the hepatic metabolic function of cKO F1 mice is age-dependent and whether older cKO F1 mice will develop metabolic diseases remain to be further explored." (PMID 36439251, 2022).
blood cancer (1 paper, 2023). "In case of DNMT3A and DNMT3B, they were found out to be overexpressed in AML patients but their expression levels were not positively correlated with blood cancer stage nor poor prognosis of AML patients." (PMID 37573395, 2023).
endocrine tumors (1 paper, 2016). "To determine if inactivation of menin increased the other three DNA methyltransferases (DNMT2, DNMT3a, and DNMT3b), we measured mRNA expression levels in the endocrine tumors from MEN1 patient samples and Men1 KO mouse models, and demonstrated no significant increase in DNMT2, DNMT3a, and DNMT3b." (PMID 26871472, 2016).
neurodegenerative disease (1 paper, 2019). A disorder of the central nervous system characterized by gradual and progressive loss of neural tissue and neurologic function. "The association of the DNMT3B -149C>T polymorphism with neurological and neurodegenerative diseases, either alone or in haplotype combination, is still controversial." (PMID 31370354, 2019).
DNMT3B also shares sentences with these, for which no sentence is quoted: idiopathic pulmonary fibrosis (3 papers); and Facial Anomalies (2); endothelial dysfunction (2); gout (2); Hirschsprung disease (2); myasthenia gravis (2); osteosarcoma (2); Rett syndrome (2); thyroid cancer (2); acute coronary syndrome (1); adenovirus infection (1); age-related macular degeneration (1); alcohol dependence (1); alcoholic hepatitis (1); alopecia (1); Alzheimer disease (1); Angelman syndrome (1); aortic aneurysm (1); arteriosclerosis obliterans (1); ataxia telangiectasia (1); autoimmune enteropathy (1); autoimmune thyroid disease (1); B vitamin deficiency (1); bipolar disorder (1); Bosma Arhinia and Microphthalmia syndrome (1); bronchiectasis (1); candidiasis (1); cardiac hypertrophy (1); cardiovascular diseases (1); chronic leukemia (1).
A further 79 diseases each share a sentence with DNMT3B in 1 paper.